RPL41 (ribosomal protein L41)
Description:
Component of the small ribosomal subunit (Probable) (Ref.8). The ribosome is a large ribonucleoprotein complex responsible for the synthesis of proteins in the cell. Interacts with the beta subunit of protein kinase CKII and stimulates phosphorylation of DNA topoisomerase II alpha by CKII.
Synonyms: L41; eL41
Tractability: Small molecule: an approved drug acts on it; a structure with a bound ligand is known; a high-quality ligand is known. PROTAC: a small molecule that binds it is known. Other modalities: a drug acting on it is in phase 2 or 3 trials.
Gene: Protein-coding gene on chromosome 12 (56,116,590 to 56,117,967, forward strand). Ensembl gene ENSG00000229117.
Subcellular location: Cytoplasm
Subcellular location (Human Protein Atlas): Endoplasmic reticulum
Pathways (Reactome):
Metabolism of proteins: Eukaryotic Translation Termination; Formation of a pool of free 40S subunits; GTP hydrolysis and joining of the 60S ribosomal subunit; L13a-mediated translational silencing of Ceruloplasmin expression; PELO:HBS1L and ABCE1 dissociate a ribosome on a non-stop mRNA; Peptide chain elongation; Ribosome Quality Control (RQC) complex extracts and degrades nascent peptide; SRP-dependent cotranslational protein targeting to membrane; ZNF598 and the Ribosome-associated Quality Trigger (RQT) complex dissociate a ribosome stalled on a no-go mRNA
Metabolism of RNA: Major pathway of rRNA processing in the nucleolus and cytosol; Nonsense Mediated Decay (NMD) enhanced by the Exon Junction Complex (EJC); Nonsense Mediated Decay (NMD) independent of the Exon Junction Complex (EJC)
Cellular responses to stimuli: Response of EIF2AK4 (GCN2) to amino acid deficiency
Developmental Biology: Regulation of expression of SLITs and ROBOs
Disease: Viral mRNA Translation
Metabolism: Selenocysteine synthesis
Gene Ontology:
Molecular function: mRNA 3'-UTR binding; mRNA 5'-UTR binding; protein binding; RNA binding; structural constituent of ribosome
Biological process: cytoplasmic translation; negative regulation of myoblast fusion; spermatogenesis; striated muscle contraction; translation
Cellular component: cytoplasm; cytosolic large ribosomal subunit; endoplasmic reticulum; cytosol; ribosome
Genetic constraint (gnomAD): Loss-of-function variants: 3 observed, 5.94 expected, observed/expected ratio (o/e) 0.5, 90% interval 0.23 to 1.29. That is too few expected variants to judge how well the gene tolerates losing a copy. Missense variants: 13 observed, 24.69 expected, observed/expected ratio (o/e) 0.53, 90% interval 0.34 to 0.84. Synonymous variants: 9 observed, 5.75 expected, observed/expected ratio (o/e) 1.57, 90% interval 0.89 to 1.94.
Diseases named in the same sentence as RPL41 in open-access papers:
RPL41 is named in the same sentence as 12 diseases in open-access papers, as found by Europe PMC text mining. Sharing a sentence is not in itself a finding about the gene and the disease. The quoted sentences say what the papers report.
lung carcinoma (2 papers, 2020 to 2025). "An early functional screening study showed that lung cancer cells were very sensitive to RPL41(ribosomal protein L41) treatment." (PMID 41451209, 2025).
breast carcinoma (1 paper, 2022). "Cluster 1 and cluster 2 had no specific enriched breast cancer signatures however cluster 1 had several ribosomal and ER stress-associated genes (Rpl41, Rps27, Rps29, Fosb, and Jund)." (PMID 35851387, 2022).
hepatocellular carcinoma (1 paper, 2025). A malignant tumor that arises from hepatocytes. "The most constantly expressed genes across that investigation were RPL41 (Ribosomal protein L41) and SFRS4 (serine and arginine rich splicing factor 4), whose combination was found to be the most reliable for normalization in hepatocellular carcinoma." (PMID 40943534, 2025).
myopia (1 paper, 2018). "Moreover, it points out that multiple associated ribosomal deficits might play a role in DBA-related phenotypes, considering the simultaneous deletion of three of them in the index case (RPS26, PA2G4 and RPL41), and it confirms the association among SLC39A5 functional disruption and severe myopia." (PMID 30524470, 2018).
ovarian carcinoma (1 paper, 2018). A malignant neoplasm originating from the surface ovarian epithelium. "In ovarian cancer, shRNA-mediated knock down of RPS7 accelerated tumor cell proliferation and silencing of RPL41, which is 13.3-fold down-regulated in Huh6 cells on CAM, leads to anchorage-independent growth of fibroblasts and accelerated tumor growth in mice." (PMID 29662633, 2018).
retinoblastoma (1 paper, 2025). A malignant tumor that originates in the nuclear layer of the retina. "In this study, we investigated the expression and function of ARL5B in retinoblastoma and further explored the underlying mechanisms, providing an experimental basis for the clinical application of RPL41 and identifying a new target for the treatment of retinoblastoma." (PMID 41451209, 2025). "Our previous research demonstrated that RPL41 inhibits the growth, migration, and invasion of retinoblastoma cells." (PMID 41451209, 2025). "These in vivo findings aligned with the in vitro changes observed in cell models, supporting the conclusion that RPL41 effectively inhibited the growth of retinoblastoma." (PMID 41451209, 2025). "This study aims to evaluate the therapeutic effect of RPL41 on retinoblastoma and elucidate its potential mechanisms." (PMID 41451209, 2025). "Based on this, we selected the ARL5B gene as the focus of subsequent research to further explore the therapeutic mechanisms of RPL41 in retinoblastoma." (PMID 41451209, 2025). "In this study, in vivo experiments demonstrated that RPL41 significantly inhibits the proliferation of ectopically transplanted retinoblastoma in nude mice." (PMID 41451209, 2025). "To elucidate the mechanism by which RPL41 inhibits retinoblastoma, we conducted mass spectrometry analysis using the retinoblastoma Y79 and Weri-RB1 cells." (PMID 41451209, 2025). "Furthermore, overexpression of ARL5B was shown to promote the migration of retinoblastoma cells and partially counteract the inhibitory effects of RPL41 on these cells." (PMID 41451209, 2025). "RPL41 inhibits the growth of subcutaneous retinoblastoma xenografts." (PMID 41451209, 2025). "Consistently, treatment with RPL41 inhibited the proliferation of retinoblastoma." (PMID 41451209, 2025). "In vitro, RPL41 treatment can effectively inhibit the proliferation, migration and invasion of retinoblastoma, and enhance the sensitivity of RB cells to carboplatin." (PMID 41451209, 2025). "Therefore, we hypothesized that RPL41 may influence the growth of retinoblastoma cells by downregulating ARL5B." (PMID 41451209, 2025). "Therefore, it could be concluded that RPL41 may exert its inhibitory effect on retinoblastoma by modulating the ARL5B/SKIP/Kinesin-1 pathway." (PMID 41451209, 2025). "RPL41 inhibits the lysosomal trafficking of the ARL5B/SKIP/Kinesin-1 signaling pathway by promoting the degradation of ATF4, thereby suppressing the growth and metastasis of retinoblastoma." (PMID 41451209, 2025). "RPL41 down-regulates the expression of ARL5B by degrading ATF4 and the impaired ARL5B-related lysosomal trafficking is a mechanism to inhibit the metastasis of retinoblastoma." (PMID 41451209, 2025).
Sepsis (1 paper, 2021). Sepsis is defined as life-threatening organ dysfunction caused by a dysregulated host response to infection. "The sub analysis of healthy versus CCI CD4+ T-lymphocytes revealed unique differential expression of five genes not seen in the analysis of all late sepsis patients (upregulated: HBB, ETS1; downregulated: SMDT1, RPL41, MTRNR2L12)." (PMID 34484194, 2021).
tumor (8 papers, 2011 to 2025). "The results showed that the intervention of RPL41 affected protein homeostasis, and a considerable number of differentially expressed genes were associated with tumor progression." (PMID 41451209, 2025). "The results of the in vivo tumorigenesis experiments demonstrated that RPL41 inhibits tumor growth and slows the progression of RB by suppressing the expression of ATF4 and ARL5B in RB cells." (PMID 41451209, 2025). "The role of RPL41 in regulating signals within the tumor immune microenvironment warrants further investigation." (PMID 41451209, 2025). "Further exploration of these candidates will contribute to a more comprehensive understanding of the anti-tumor mechanisms of RPL41 beyond the ATF4-ARL5B axis." (PMID 41451209, 2025). "In the SP2/0 myeloma mice model infected with T. spiralis, genes encoding RpL41, NKTR, Rbbp4, and ANXA2 were enriched in tumor cells, suggesting a potential role in tumor growth inhibition." (PMID 40402283, 2025). "This study systematically investigated the mechanism by which RPL41 exerts its therapeutic effects in tumor treatment." (PMID 41451209, 2025). "Ribosomal protein L41 (RPL41) is a tumor suppressor and its downregulation and deletions are frequently detected in human cancers." (PMID 39261452, 2024). "RPL41 can induce the degradation of the activating transcription factor 4 (ATF4) to regulate tumour cell death, cell cycle, and chemosensitivity." (PMID 34993140, 2021). "To further investigate whether RPL41 can regulate the growth of RB in vivo, we established an ectopic RB nude mouse model and administered the peptide adjacent to the tumor on the third day following successful model establishment." (PMID 41451209, 2025). "Consistent with the previous verification, immunohistochemical staining of tumor tissues harvested from nude mice revealed that RPL41 treatment led to decreased expression levels of ATF4 and ARL5B in RB tissue, suggesting that RPL41 could inhibit the expression of these proteins." (PMID 41451209, 2025). "Mitochondrial rpL41 targets the activating transcription factor 4 (ATF4), a major regulator of tumor cell survival, for degradation contributing to sensitize tumor cells to chemotherapy." (PMID 27835895, 2016). "RPL41 is down-regulated or absent in many human tumors, and it is considered to be a promising tumor suppressor gene." (PMID 41451209, 2025). "Three genes are relevant to this locus: RPL41, a ribosomal protein not considered to be related to the immune system; ZC3H10, a zinc finger protein related to tumour growth; and ESYT1, a synaptotagmin-like protein of unknown function." (PMID 21779181, 2011).
RPL41 also shares sentences with these, for which no sentence is quoted: cancer (3 papers); infection (1); osteosarcoma (1); prostate carcinoma (1).